SOX11 (SRY-box transcription factor 11)
Diseases named in the same sentence as SOX11 in open-access papers (continued):
Sharing a sentence is not in itself a finding about the gene and the disease.
epilepsy (2 papers, 2017 to 2023). A brain disorder characterized by episodes of abnormally increased neuronal discharge resulting in transient episodes of sensory or motor neurological dysfunction, or psychic dysfunction. "miR-212-3p and miR-132-3p work synergistically to control Sox11 expression in the setting of epilepsy." (PMID 28380454, 2017).
head and neck cancer (2 papers, 2019 to 2020). A primary or metastatic malignant neoplasm affecting the head and neck. "The main purpose of our study is to investigate if SOX11 promotes the progression of oral/head and neck cancer." (PMID 30922366, 2019). "Further studies are warranted to investigate if SOX11 is essential for early development of oral/head and neck cancer." (PMID 30922366, 2019). "In summary, we have demonstrated that SOX11 promotes head and neck cancer progression via the regulation of SDCCAG8." (PMID 30922366, 2019). "In addition, both Sox11 gene and protein expression levels was significantly upregulated in highly invasive head and neck cancer cell lines UM1 and UMSCC5 when compared to low invasive UM2 and UMSCC6 cell lines." (PMID 30922366, 2019). "Nevertheless, the functional role of SOX11 in oral/head and neck cancer remains unknown." (PMID 30922366, 2019).
injury (2 papers, 2025). Damage inflicted on the body as the direct or indirect result of an external force, with or without disruption of structural continuity. "Upregulation of SOX11 expression has been shown to enhance recovery from ischemic nerve injury." (PMID 40485217, 2025). "Beyond the IGF2BP2/SOX11 axis identified in our study, other mechanisms may also play a role in regulating OM‐MSC neuronal differentiation and the repair of ICH‐induced brain injury." (PMID 40485217, 2025). "Beyond direct regulation of Cbln2, SOX11 may influence broader transcriptional programs through interactions with downstream factors such as ATF3 and c-JUN, both of which are well-established contributors to neuropathic pain following nerve injury." (PMID 41162740, 2025).
intellectual disability syndrome (2 papers, 2018 to 2021). "SOX11 is a key Transcription Factor (TF) in the regulation of embryonic and adult neurogenesis, whose mutation has recently been linked to an intellectual disability syndrome in humans." (PMID 29973868, 2018).
liver cancer (2 papers, 2022). An epithelial or non-epithelial malignant neoplasm that arises from the liver. "SOX11 promotes apoptosis of liver cancer cells through Wnt signaling pathway." (PMID 35033084, 2022).
lung adenocarcinoma (2 papers, 2022 to 2025). A carcinoma that arises from the lung and is characterized by the presence of malignant glandular epithelial cells. "Through online survival analysis, we found that in lung adenocarcinoma, patients with low SOX11 expression have a better prognosis." (PMID 35033084, 2022).
mesothelioma (2 papers, 2022 to 2025). A usually malignant and aggressive neoplasm of the mesothelium which is often associated with exposure to asbestos. "As for the types of genetic alterations in SOX11 in different cancers, mutations were the most frequent, particularly in UCEC, LUSC, CESC, STAD, ESCA, COAD/READ, mesothelioma (MESO), ACC, PAAD and HNSC." (PMID 36551589, 2022). "The proteins that were unique to mesothelioma samples (cell line and PE samples) were MAGED4, PRAME, WT1, ACRBP, EPHA2 and SOX11." (PMID 39921204, 2025).
microphthalmia (2 papers, 2014 to 2016). Congenital or developmental anomaly in which the eyeballs are abnormally small. "Moreover, decreased gene dosage from a segmental deletion encompassing the SOX11 locus resulted in microphthalmia and related ocular phenotypes." (PMID 25010521, 2014). "First, Bmp7 null mice display microphthalmia and optic fissure defects, similar to sox11 null mice." (PMID 25010521, 2014).
Oral Cancer (2 papers, 2019 to 2020). "Patients who carried SOX11 rs77996007 TC were at a higher risk of oral cancer compared with the controls (OR = 1.218; 95% CI = 1.026–1.446)." (PMID 32586027, 2020). "Our results indicate that the allelic effects of SOX11 SNPs increase the risk of oral cancer based on environmental factors, such as tobacco smoking and betel quid chewing." (PMID 32586027, 2020). "In the present study, we observed that the combined effect of environmental factors and SOX11 polymorphisms considerably increased the risk of oral cancer." (PMID 32586027, 2020). "Because the study included only the discovered population and there was no independent study to confirm these findings, our findings regarding the association between the SOX11 variant and oral cancer should be considered preliminary." (PMID 32586027, 2020). "The allele frequencies of SOX11 rs77996007, rs66465560, and rs68114586 were predominantly distributed in the controls and patients with oral cancer heterozygous for TC, homozygous for TT, and homozygous for Ins/Ins." (PMID 32586027, 2020). "However, the clinical significance of SOX11 polymorphisms in oral cancer and their association with oral cancer risk are unclear." (PMID 32586027, 2020). "Moreover, in oral cancer patients, SOX11 rs77996007 variants were significantly associated with large tumor size." (PMID 32586027, 2020). "Furthermore, oral cancer patients who carried SOX11 rs77996007 “TC + CC” variants were significantly associated with large tumor size (AOR, 1.324; 95% CI, 1.047–1.674; p = 0.019)." (PMID 32586027, 2020). "The present study is the first to explore the association between SOX11 SNPs and oral cancer." (PMID 32586027, 2020). "We investigated the role of SOX11 genetic polymorphisms in the clinical status of oral cancer." (PMID 32586027, 2020). "However, the role of SOX11 polymorphisms in oral cancer has rarely been discussed." (PMID 32586027, 2020). "In conclusion, our results suggest that SOX11 rs77996007 is involved in oral cancer progression and clinical characteristics." (PMID 32586027, 2020). "More importantly, both Sox11 gene and protein expression was significantly overexpressed in recurrent oral cancer tissues when compared to paired primary oral cancer tissues." (PMID 30922366, 2019). "In addition, the mechanism through which SOX11 SNPs regulate the development of oral cancer still requires further investigation." (PMID 32586027, 2020). "Our results shown that SOX11 polymorphisms carriers with betel quid chewing were found to have an 8.38- to 9.23-fold risk to have oral cancer compared to SOX11 wild-type carriers without betel quid chewing." (PMID 32586027, 2020). "We revealed the importance of SOX11 variations in the development of oral cancer." (PMID 32586027, 2020). "Our results suggest that SOX11 rs77996007 is involved in the tumor progression of oral cancer." (PMID 32586027, 2020). "Moreover, recent studies have reported that both the SOX11 gene and protein expression were significantly overexpressed in recurrent oral cancer tissues and may promote oral cancer invasion and progression." (PMID 32586027, 2020). "However, no studies have explored the correlation between SOX11 SNPs and oral cancer." (PMID 32586027, 2020).
ovarian serous carcinoma (2 papers, 2021 to 2023). "In the present study, we were able to show for the first time a positive although statistically marginal correlation of SOX11 expression in ovarian serous carcinomas with the presence of metastatic disease at the time of diagnosis." (PMID 37760985, 2023). "Similarly, analyses of SOX11 and ovarian serous carcinoma turnover, mesenchymal stem cell metastasis, and migration in cell lines are needed to better understand the possible role of SOX11 in this regard." (PMID 37760985, 2023). "Another study assessed the protein expression of E-CADH, N-CADH, P-cadherin, ZEB1, HMGA2, RAB25, CD24, NCAM, SOX11, and VIM in 100 tubo-ovarian serous carcinoma effusions and found a limited prognostic role of the markers alone or in combination." (PMID 34070214, 2021). "The results of our study are only preliminary and, by no means, allow for generalized conclusions on the role of SOX11 as a biomarker for activation of EMT in serous ovarian carcinoma." (PMID 37760985, 2023). "This group tried to shed light on the possible role of SOX11 in EMT in ovarian serous carcinoma; however, metastatic pleural effusions and not the primary tumor mass were investigated, in contrast to our investigation." (PMID 37760985, 2023).
pancreatic ductal adenocarcinoma (2 papers, 2020 to 2022). An infiltrating adenocarcinoma that arises from the epithelial cells of the pancreas. "Thus, SOX11 and other transcription factors are important in the diagnosis of SPNs and in distinguishing them from Pan NETs and pancreatic ductal adenocarcinomas." (PMID 33298094, 2020).
rectum adenocarcinoma (2 papers, 2022 to 2025). An adenocarcinoma arising from the rectum. "Finally, we examined expression of SOX11 and the human counterparts of a selection of Sox11-dependent genes in colon and rectum adenocarcinoma samples upon CMS stratification." (PMID 40393982, 2025).
Splenomegaly (2 papers, 2014 to 2016). Abnormal increased size of the spleen. "Sox11-negative MCL cases mostly demonstrate an indolent course and a non-nodal presentation with splenomegaly and high WBC and lymphocyte counts when compared with SOX11-positive cases." (PMID 27119356, 2016).
Wilms tumor (2 papers, 2013 to 2014). An embryonal neoplasm characterized by the presence of epithelial, mesenchymal, and blastema components. "Activated SOX11 expression has been described in Wilms tumor, a classic example of an embryonic tumor, often characterized by retention of embryonic cellular structures within the tumor-bearing kidney." (PMID 23506684, 2013).
abscess (1 paper, 2023). An inflammatory process characterized by the accumulation of pus within a newly formed tissue cavity which is the result of a bacterial, fungal, or parasitic infection or the presence of a foreign body. "We observed single dispersed (<1%) SOX11-positive cells in two cases (gliosis around invasive meningioma and abscess), showing weak to strong immunoreactivity." (PMID 37568909, 2023).
acute monocytic leukemia (1 paper, 2010). Acute monoblastic leukemia (AML-M5), is one of the most common subtypes of acute myeloid leukemia (AML) that is either comprised of more than 80% of monoblasts (AML-M5a) or 30-80% monoblasts with (pro)monocytic differentiation (AML-M5b). "The methylation status of the SOX11 promoter was assessed in nineteen cell lines, originating from different B cell malignancies, including eight MCL, three DLBCL, four FL, three BL and one acute monocytic leukemia (MONO-L)." (PMID 20624318, 2010).
asplenia (1 paper, 2011). "A thorough assessment of the developmental mechanisms responsible for asplenia in the Sox11 null mutant has not been presented." (PMID 21738788, 2011).
bladder tumor (1 paper, 2018). "SOX11 was up-regulated in bladder tumor tissues with a fold change value of 11.56." (PMID 30134837, 2018).
brain malformations (1 paper, 2016). "That two of our cases had brain malformations provides further evidence that SOX11 functions in human neurodevelopment." (PMID 26543203, 2016).
carcinoids (1 paper, 2022). "The high specificity of SOX11 helps in distinguishing SCLCs and LCNECs from NSCLCs with NE differentiation and carcinoid tumors." (PMID 34996493, 2022). "Beneficially, SOX11 hardly detected in NSCLCs, particularly LCCs, and carcinoids, exhibiting a significantly better specificity than all the other 4 markers in the diagnosis of HG-NECs." (PMID 34996493, 2022). "For carcinoids, in contrast to diffuse expression of INSM1, SYN, CGA and CD56 in most of the cases, positivity staining of SOX11 was observed in none of typical carcinoids (0/25) and only 1/12 of atypical carcinoids." (PMID 34996493, 2022). "SOX11 constitutes an important complement to the present panel of NE markers to distinguish HG-NECs from carcinoid and non-NE cancers, especially LCCs." (PMID 34996493, 2022).
clear cell ovarian cancer (1 paper, 2011). "It is not clear whether SOX11 defines endometrioid carcinoma of a specific origin, since it has been suggested that they, like clear cell ovarian cancer, may be derived from endometriotic deposits in contrast to the surface epithelial layer of the ovary or distal fallopian tube." (PMID 21943380, 2011).
cleft palate (1 paper, 2020). Cleft palate is a fissure type embryopathy that affects the soft and hard palate to varying degrees. "Of the Sox transcription factors, only SOX11 has been associated with a patient presenting with cleft palate." (PMID 33424631, 2020). "Whether Sox11 is functionally important for the removal of the epithelial seam is unknown, but this could explain occurrences of cleft palate in some CSS patients." (PMID 33424631, 2020).
colorectal tumors (1 paper, 2025). "Nonetheless, we believe that the contribution of Sox11 to TGF-β1-induced pEMT and collective invasion in a mouse organoid model for intestinal carcinogenesis reflects cancer-promoting activities of SOX11 in human colorectal tumors." (PMID 40393982, 2025).
conductive hearing loss (1 paper, 2023). "Otitis media leading to conductive hearing loss has been reported in CSS patients with SOX11 variants, but sensorineural hearing loss associated with inner ear malformations has not been recorded as a significant complication of CSS caused by SOX11 variants." (PMID 36369738, 2023).
diabetes (1 paper, 2021). "Likewise, the reduced SOX11 expression in D13.1βHet SOX2+ progenitors and early MPCs found in our HNF1B-deficient pancreatic cell differentiation model could at least partially explain the organ hypoplasia found in patients with HNF1B-associated diabetes." (PMID 34450036, 2021).
dilated cardiomyopathy (1 paper, 2022). Cardiomyopathy which is characterized by dilation and contractile dysfunction of the left and right ventricles. "SOX11 was also found to be positively associated with disease-related pathways, including dilated cardiomyopathy, hypertrophic cardiomyopathy and maturity-onset diabetes of the young." (PMID 36551589, 2022).
embryonal carcinoma (1 paper, 2009). A non-seminomatous malignant germ cell tumor characterized by the presence of large germ cells with abundant cytoplasm resembling epithelial cells, geographic necrosis, high mitotic activity, and pseudoglandular and pseudopapillary structures formation. "Since both Sox4 and Sox11 are implicated in neuronal differentiation and glial maturation processes, we examined both Sox4 and Sox11 sense and antisense transcript expression in proliferating and differentiating P19 (embryonal carcinoma cells) and in embryonic NSPCs grown as neurospheres." (PMID 19799774, 2009).
endometrioid carcinomas (1 paper, 2011). "Further studies are needed to determine if SOX11 also is associated with differentiation pattern in endometrioid carcinomas, although they are known to mostly be well differentiated, in contrast to our cohort." (PMID 21943380, 2011). "In this study, we demonstrated that SOX11 was associated with an improved survival among patients with high-grade carcinomas and potentially also with endometrioid carcinomas, although the latter needs to be statistically confirmed in a larger cohort of patients." (PMID 21943380, 2011).
Ewing sarcoma (1 paper, 2023). A small round cell tumor that lacks morphologic, immunohistochemical, and electron microscopic evidence of neuroectodermal differentiation. "In Ewing sarcoma cells, the exogenous expression of SOX11 impaired cell growth, whereas the expression of a DBD-deleted mutant did not." (PMID 36658220, 2023).
Gliosis (1 paper, 2023). Gliosis is the focal proliferation of glial cells in the central nervous system. "The sensitivity and specificity of the negative staining for the diagnosis of gliosis were as follows: EGFR—100% sensitive, 32.8% specific; MEOX2—97.7% sensitive, 37.5% specific; SOX11—79.5% sensitive, 46.6% specific and INSM1—97.7% sensitive, 47.8% specific." (PMID 37568909, 2023).
HCMV infection (1 paper, 2024). "Others have demonstrated that SOX11 is both necessary and sufficient for the development of hair cells in the inner ear, and the data suggest that HCMV infection reduced SOX11 expression at both timepoints." (PMID 38440980, 2024).
Hip dysplasia (1 paper, 2023). The presence of developmental dysplasia of the hip. "The spectrum of SOX11 variant‐related CSS9 disease phenotypes has expanded further in recent years to include certain congenital kidney and urinary tract abnormalities, cardiac anomalies, cleft palate, and hip dysplasia." (PMID 36369738, 2023).
Hodgkins lymphoma (1 paper, 2011). A heterogeneous group of malignant lymphoid neoplasms of B-cell origin characterized histologically by the presence of Hodgkin and Reed-Sternberg (HRS) cells in the vast majority of cases. "In MCL cell lines (n = 8), SOX11 was mostly unmethylated (median/IQR = 0.14/0.17) whereas all non-MCL cell lines including T-ALL (n = 1), DLBCL (n = 3), BL (n = 1) and Hodgkin lymphoma (n = 4) were strongly methylated (median/IQR = 0.91/0.03)." (PMID 21738649, 2011).
Hypoglycemia (1 paper, 2025). A decreased concentration of glucose in the blood. "Further studies are needed to elucidate the role of hypoglycemia-induced SOX11 expression in RGCs, as well as its potential link with autophagy." (PMID 41294828, 2025).
intestinal tumor (1 paper, 2026). "Furthermore, we investigated a case of SOX11-negative indolent MCL (iMCL) with late relapse characterized by extensive extranodal dissemination, including peripheral blood leukemization and intestinal tumor masses." (PMID 41802856, 2026).
knee osteoarthritis (1 paper, 2013). "We find that SOX11 is mainly expressed in the weight-bearing areas of knee joints, and its expression is decreased in degraded cartilage during progression of knee osteoarthritis in both mice and humans." (PMID 23356643, 2013).
large cell carcinoma (1 paper, 2022). A malignant epithelial neoplasm composed of large, atypical cells. "We evaluated the immunohistochemical expression of SOX11, a transcription factor involved in neurogenesis, in pulmonary NE tumors and large cell carcinomas (LCCs)." (PMID 34996493, 2022).
metastatic cancers (1 paper, 2022). A carcinoma which has spread from the original site of growth to another anatomic site. "However, the expression level and genetic alterations of SOX11 in metastatic cancers remain unknown." (PMID 36551589, 2022).
metastatic disease (1 paper, 2023). "In particular, the one case in our cohort that was negative for E-cadherin displayed an increased expression of SOX11, calculated as 70%, and was an HG serous carcinoma with metastatic disease at diagnosis." (PMID 37760985, 2023).
metastatic melanoma (1 paper, 2024). A melanoma that has spread from its primary site to another anatomic site. "Here, we present a case of dedifferentiated metastatic melanoma with the loss of four diagnostic melanocytic markers, but a gain of SOX-11." (PMID 39258061, 2024). "Here we report a challenging case of a 59-year-old male with splenic metastatic melanoma which revealed a loss of four diagnostic melanocytic markers including S100, SOX-10, HMB45, and MART-1, but a gain of SOX-11." (PMID 39258061, 2024). "In our case, SOX-11 was found to be overexpressed in metastatic melanoma." (PMID 39258061, 2024). "We have presented an interesting case of quadruple negative metastatic melanoma with gain of SOX-11 expression and various genetic mutations." (PMID 39258061, 2024).
myopia (1 paper, 2025). "Therefore, we propose that SOX11 may directly or indirectly affect proteins with strong links to high myopia, such as COL9A1, COL2A1, and COL11A1, by affecting the expression or function of SOX4, ultimately causing the clinical phenotype of eoHM and dystrophy of cone-rod cells in CSS9 individuals." (PMID 40933692, 2025).